CXCR4 (C-X-C motif chemokine receptor 4)
Diseases named in the same sentence as CXCR4 in open-access papers (continued):
Sharing a sentence is not in itself a finding about the gene and the disease.
lupus (continued). "As suggested by the basopenia observed in patients with active SLE and by the transient basopenia induced by PGD2 injection in mice, PGD2 was sufficient to induce CXCR4-dependent basophil recruitment to SLO in lupus-prone mice." (PMID 29463843, 2018). "CXCR4 antagonists showed some efficacy in murine lupus models, especially on autoantibody production and lupus-like nephritis." (PMID 29463843, 2018). "The direct role of CXCL12/CXCR4 network to recruit immune cells in the lupus nephritic kidney is demonstrated in another study with administration of a CXCR4 antagonist in B6.SleYaa lupus-prone mice." (PMID 27403037, 2016). "Blocking the interaction of CXCL12/CXCR4 in lupus-prone mice reveals their contributions to both systemic autoimmune responses in secondary lymphoid organs and local renal inflammation." (PMID 27403037, 2016). "Because the B cells of lupus mice exhibited high expression levels of CXCR4, we monitored the B cell responsiveness to CXCL12 in term of actin polymerization, chemotaxis, proliferation and signaling." (PMID 25909640, 2015). "Strikingly, our study demonstrated that lupus mice infected with live malaria parasite exhibit a restored surface expression of CXCR4 on B cells." (PMID 25909640, 2015). "The other chemokine member, CXCL12 and its receptor CXCR4, have been shown to be markedly elevated in infected lupus mice via activation of the NF-κB signaling pathway." (PMID 26310926, 2015). "In accordance, the overexpression of CXCR4 has been demonstrated on peripheral blood B cells from active systemic lupus erythematosus (SLE) patients, especially those with lupus nephritis, a complication associated with heightened disease severity in flares-up." (PMID 38519141, 2024). "Elevated CXCR4 expression has been previously observed in lupus patients’ B cells." (PMID 34889940, 2022). "In addition, aberrant CXCR4 expression has been shown to correlate with autoimmunity in lupus and CXCL12/CXCR4 signaling regulates T cell migration to target organs in Sjögren’s syndrome." (PMID 35947323, 2022). "As it was claimed that the CXCR4 pathway is deregulated in lupus, we examined if LIT-927 might correct some of these abnormalities." (PMID 34744730, 2021). "In the present study, we provide novel insights into the CXCL12/CXCR4 axis biology in lupus." (PMID 34744730, 2021). "It is worth noting that the hub gene CXCR4 was previously found abundant in kidney biopsies from SLE patients, and CXCR4 antagonist administration could improve disease severity and nephritis in murine lupus models." (PMID 33304383, 2020). "As far as B cells are concerned, aberrant expression of the chemokine receptor CXCR4 on lupus B cells might contribute to subsequent autoantibody production." (PMID 31575058, 2019). "SDF-1/CXCR4 axis can induce intracellular signalings involved in inflammatory response, cell survival, and proliferation, playing a vital role in some diseases such as kidney diseases and systemic lupus erythematosus." (PMID 29849929, 2018). "Importantly, both CXCL12 and CXCR4 expressions are increased in the kidney of diseased lupus-prone mice, indicating migration of CXCR4+ cells into the kidney as LN progresses." (PMID 27403037, 2016). "In lupus-prone mouse models, CXCR4 is consistently increased in various immune cell populations including B cells, plasma cells, T cells, neutrophils, and monocytes in the circulation and spleen of diseased mice, suggesting enhanced chemotaxis of these cells towards CXCL12." (PMID 27403037, 2016). "Moreover, a recent study reported that the CXCR4/CXCL12 axis controls auto-immunity in lupus patients following influenza vaccine." (PMID 25909640, 2015). "Similarly, CXCR4 hyper-expression or -activity has been reported in various leukocyte subsets of lupus mouse models." (PMID 23244336, 2012).
lupus (continued). "Furthermore, the B cells of lupus mice exhibited an increased proliferative capacity; aberrant overexpression of the chemokine receptor CXCR4; and a marked elevation in responsiveness to their cognate ligand (CXCL12) via aberrant activation of the PI3K/AKT, NFκB and ERK signaling pathways." (PMID 25909640, 2015). "This increase in CXCR4 expression may be due to the occurrence of inflammation in lupus mice." (PMID 25909640, 2015). "MRL/lpr lupus-prone mice were treated with the DPP-4 inhibitor linagliptin, either alone or in combination with the CXCL12/CXCR4 axis antagonist AMD3100." (PMID 41601976, 2026). "Supporting the role of CXCR4 in ASC homing and retention in the BM, even in the pro-inflammatory milieu of the lupus BM20, this receptor was expressed in the majority of BM PC whereas CXCR3 expression was rare on SLE BM PC." (PMID 38429276, 2024). "Supporting the role of CXCR4 in ASC homing and retention in the BM, even in the pro-inflammatory milieu of the lupus BM, this receptor was expressed in the majority of BM PC whereas CXCR3 expression was rare on SLE BM PC." (PMID 37461641, 2023). "In addition to B cells and monocytes, CXCR4 is also highly expressed on CD4+ and CD8+ T cells in both lupus patients and lupus-prone mice, where it contributes to their aberrant activation and renal infiltration." (PMID 41601976, 2026). "In addition, CXCR4 in B cells and CD4+ T cells was upregulated more in patients with systemic lupus erythematosus than in controls." (PMID 37224769, 2023). "Altogether, these data illustrate that in lupus, major alterations occur in the CXCL12/CXCR4 axis, and suggest that measuring the expression levels of CXCL12 and/or CXCR4 could be useful to follow the activity status of patients." (PMID 34744730, 2021). "To conclude, our present results suggest that by hampering the interaction between CXCL12 and CXCR4, the LIT-927 neutraligand limits the signaling occurring into T and B cells in lupus context with potential favorable outcome on the course of the lupus disease that needs further investigations." (PMID 34744730, 2021). "In this context, we observed that the surface expression of CXCR4 on the B cells of lupus mice was significantly up-regulated compared with the non-lupus control group (* P < 0.05)." (PMID 25909640, 2015). "The analysis of peripheral blood B cells by flow cytometry showed that the surface expression of CXCR4 was up-regulated on the surface of B cells of lupus mice, whereas there was no detectable change in the surface expression of CCR6, CCR7 and CXCR5." (PMID 25909640, 2015). "In a representative experiment, we found that, unlike CCR6, CCR7 and CXCR5, the surface expression of CXCR4 was substantially up-regulated on the surface of B cells of lupus mice compared with the control non-lupus mice." (PMID 25909640, 2015). "Infecting lupus mice with live, but not dead, malaria parasite restored the surface expression of CXCR4 on the B cells." (PMID 25909640, 2015). "CXCR4 and its ligand CXCL12 may take over as suggested by the beneficial effect of a CXCR4 antagonist peptide in another mouse model of lupus (B6.Sle1Yaa;)." (PMID 23520491, 2013). "The study was extended to the expression of CXCR7, which is another receptor for CXCL12 but, unlike CXCR4, it has never been investigated in the context of lupus pathogenesis." (PMID 23244336, 2012). "In the same vein, expression levels of CXCL12 and its two cognate receptors CXCR4 and CXCR7 have been found to be altered in SLE patients and murine models of lupus." (PMID 34744730, 2021). "Surprisingly, the surface expression of CXCR4 on the B cells of lupus mice infected with live malaria parasite, but not gamma-irradiated malaria parasite, was significantly restored compared with the non-infected lupus group (# P < 0.05, n = 5)." (PMID 25909640, 2015).
lupus (continued). "Interestingly, infecting lupus mice with live but not gamma-irradiated malaria parasite restored a normal proliferative capacity, surface expression of CXCR4 and B cell response to CXCL-12." (PMID 25909640, 2015). "Therefore, the enhanced co-expression of CXCR4 and CXCR3 in circulating SLE ASC suggests a strong capability of these cells to migrate into inflamed Lupus kidneys, whether as a primary or a secondary amplifying event." (PMID 37461641, 2023). "Here, we report that PGD2 induces a CXCR4-dependent accumulation of basophils in SLO, and that antagonizing PTGDR in vivo in two distinct lupus-like mouse models prevented this recruitment in SLO without impacting other cell type populations but the short-lived plasma cells." (PMID 29463843, 2018).
oral squamous cell carcinoma (34 papers, 2007 to 2025). "In this study, we reported for the first time that CXCR4 expression within the tumor vasculature is significantly associated with higher pathological grades of human oral squamous cell carcinoma (OSCC) (p<0.03)." (PMID 41210695, 2025). "The CXCL12/CXCR4 pathway can recruit macrophages in oral squamous cell carcinoma through cancer-associated fibroblast (CAF) to promote the transformation of cancer stem cells." (PMID 36308553, 2023). "In oral squamous cell carcinoma, RNAi-mediated CXCR4 silencing caused tumor cell apoptosis in vitro and in vivo." (PMID 26954567, 2016). "C-X-C chemokine receptor type 4 (CXCR4) plays a significant role in the tumor microenvironment of oral squamous cell carcinoma (OSCC), but its specific function in bone invasion remains poorly understood." (PMID 41413548, 2025). "To analyze the correlation between CXCR4-expressed tumor vessels and clinical parameters, we stained the CXCR4 in human oral squamous cell carcinoma (OSCC) and normal tissue microarrays." (PMID 41210695, 2025). "The CXCL12/CXCR4 axis plays a pivotal role in the progression of various malignancies, including oral squamous cell carcinoma (OSCC)." (PMID 36300800, 2023). "The SDF-1α/CXCR4 axis regulates inflammatory responses in diseases such as chronic skin inflammation, osteoarthritis, acute peritonitis, and colon and oral squamous cell carcinoma." (PMID 36159583, 2022). "We uncovered, for the first time, the importance of combinatorial expression of stem cell related molecules CXCR-4 and CD-133 as possible biomarkers to predict poor prognosis of oral squamous cell carcinoma." (PMID 34885003, 2021). "The oral squamous cell carcinoma cases with CXCR-4/PKC-δ, CXCR-4/CD133 and CD133/PKC-δ double positivity showed poor survival rates." (PMID 34885003, 2021). "A statistically significant difference was found between CXCR4 and grades of oral squamous cell carcinoma (p < 0.02)." (PMID 34885003, 2021). "It was shown that CXCR4 was expressed in 50–60% of oral squamous cell carcinoma (OSCC) clinical cases." (PMID 31336612, 2019). "The CXCL12/CXCR4 system also facilitates lymph node metastatic potential in oral squamous cell carcinoma by enabling EMT69." (PMID 29743718, 2018). "The targeted silencing of CXCR4 inhibits epithelial-mesenchymal transition in oral squamous cell carcinoma." (PMID 28415580, 2017). "The decreased expression of miR‐9 leads to the constitutive activation of β‐catenin via the overexpression of CXCR4 in oral squamous cell carcinoma (OSCC) cells." (PMID 26871266, 2016). "The goal of the present study was to investigate alterations of CXCL12/CXCR4 in oral premalignant lesions and oral squamous cell carcinoma (OSCC)." (PMID 22496601, 2012). "We have demonstrated that the stromal cell-derived factor-1 (SDF-1; CXCL12)/CXCR4 system is involved in the establishment of lymph node metastasis in oral squamous cell carcinoma (SCC)." (PMID 19671192, 2009). "Therefore, this study aimed to explore the effect of CXCR4 antagonism on various blood vessels present within the oral squamous cell carcinoma (OSCC) tumor stroma." (PMID 41210695, 2025). "Moreover, CXCR4 knockdown by small interfering RNA was shown to inhibit cell proliferation and invasion of oral squamous cell carcinoma cells." (PMID 21349176, 2011). "In oral squamous cell carcinoma (OSCC), miR-139-5p inhibited tumorigenesis by targeting HOXA9 and CXCR4." (PMID 34576110, 2021). "In this study, we have investigated the expression pattern of CXCR4, PKC-δ and CD133 in oral squamous cell carcinoma." (PMID 34885003, 2021). "On the other hand, the significance of CXCR-4/CD133 and CXCR-4/PKC-δ double positivity is untouched in oral squamous cell carcinoma." (PMID 34885003, 2021). "In the present study, the univariate analysis revealed the prognostic significance of CXCR-4, PKC-δ and CD133 in oral squamous cell carcinoma." (PMID 34885003, 2021).
oral squamous cell carcinoma (continued). "Immunohistochemistry and double immunofluorescence was used to investigate the co-localization of CXCR-4, PKC-δ and CD133 in the human tissues and cell lines of oral squamous cell carcinoma." (PMID 34885003, 2021). "In this study, we have investigated the importance of CXCR-4 and CD133 or PKC-δ double positivity in the prognosis of oral squamous cell carcinoma." (PMID 34885003, 2021). "Additionally, CAFs draw monocytes through the CXCL12/C-X-C motif chemokine receptor 4 (CXCR4) signaling pathway and prompt their differentiation into M2-type macrophages, further promoting the formation of M2-type TAMs in oral squamous cell carcinoma." (PMID 40038745, 2025). "The co-expression of CXCR-4 and PKC-δ has been found in some cells of oral squamous cell carcinoma." (PMID 34885003, 2021). "CXCR4 is a chemokine receptor crucial in tumor progression, although the angiogenic role of CXCR4 in oral squamous cell carcinoma (OSCC) has not been investigated." (PMID 31336612, 2019).
diffuse large B-cell lymphoma (33 papers, 2014 to 2025). "CXCR4 signaling has been proposed as an acquired resistance mechanism in BCR-dependent diffuse large B-cell lymphomas." (PMID 37629071, 2023). ",10▪ CXCR4 mutations are essentially unique to WM, with only rare reports in marginal zone lymphoma (MZL) and ABC diffuse large B-cell lymphoma (DLBCL) cases." (PMID 35309816, 2019). "The CXCL12/CXCR4 pathway is involved in several aspects of tumor pathogenesis, promoting tumor vasculogenesis and angiogenesis in tumor stem-like glioma cells or regulating lymphoid tumor microenvironment in diffuse large B-cell lymphoma (DLBCL)." (PMID 39273392, 2024). "However, in diffuse large B cell lymphoma, co-expression of CXCR4 and CXCR7 is associated with a higher survival rate, while CXCR7+/CXCR4- patients show a poorer survival." (PMID 33530455, 2021). "This study explores the interaction between CD19 and CXCR4 signaling in the context of B-cell lymphomas, particularly focusing on diffuse large B-cell lymphoma (DLBCL) and Waldenström Macroglobulinemia (WM)." (PMID 40076664, 2025). "In diffuse large B-cell lymphoma (DLBCL), the expression of the chemokine receptor CXCR4 is involved in the dissemination of malignant B cells and is a marker of poor prognosis." (PMID 29920526, 2018). "Moreover, a recent study in diffuse large B cell lymphoma (DLBCL) showed that active super-enhancers (SEs) harboring hypermutation are linked to the upregulation of oncogenes related to B cell developmental and malignant transformation, including BCL6, BCL2, and CXCR4." (PMID 39724337, 2025). "Molecular docking on the CXCR4 crystal structure allowed us to rank the selection and identify those candidate molecules with potential antitumor activity against diffuse large B-cell lymphoma (DLBCL)." (PMID 39273392, 2024). "In mucosa-associated lymphoid tissue (MALT) neoplasms upregulation of ACKR3 and concomitant downregulation of CXCR4 could play a role in the transformation to diffuse large B-cell lymphoma (DLBCL)." (PMID 29156704, 2017). "Overexpression of CXCR4 was detected with [68Ga]pentixafor PET/CT in lymphoplasmacytic lymphoma, marginal zone lymphoma, diffuse large B cell lymphoma, follicular lymphoma, mantle cell lymphoma, unclassified indolent B cell lymphoma, and enteropathy associated T cell lymphoma." (PMID 32757068, 2020). "Diffuse large B cell lymphoma (DLBCL) is characterized by the dissemination of neoplastic B cells throughout the organism which is under the control of chemokines such as Stromal Derived Factor 1 (SDF-1) and its receptor CXCR4." (PMID 30373149, 2018).
small cell lung carcinoma (33 papers, 2009 to 2026). Small cell lung cancer (SCLC) is a highly aggressive malignant neoplasm, accounting for 10-15% of lung cancer cases, characterized byrapid growth, and early metastasis. "In addition, CXCR4 was upregulated in CTCs derived from different tumor types such as small cell lung cancer, and this expression was associated with poorer PFS." (PMID 31370904, 2019). "For instance, in small-cell lung cancer, miR-1 directly suppresses C-X-C motif chemokine receptor 4 (CXCR4), leading to the subsequent inhibition of FOXM1 and ribonucleotide reductase M2 (RRM2), thereby impeding tumor progression." (PMID 41373864, 2025). "Expanding the potential of CXCR4 targeting beyond hematologic malignancies, recent studies have also explored the use of 212Pb/203Pb-labeled agents in CXCR4-expressing tumors, demonstrating therapeutic efficacy in murine models of small cell lung cancer." (PMID 40227793, 2025). "The evaluation of the CXCR4 expression in small cell lung cancers showed that it was expressed with high intensity in almost all of the SCLC samples." (PMID 39457017, 2024). "CXCR4 is also emerging as a valuable target in atypical lung carcinoid and small cell lung cancer, and can be targeted with the radiolabeled ligand Pentixafor and Pentixather." (PMID 35454817, 2022). "This study investigated the feasibility of CXCR4-directed imaging of small cell lung cancer (SCLC) with positron emission tomography/computed tomography (PET/CT) using the radiolabelled chemokine ligand [68Ga]Pentixafor." (PMID 26843617, 2016). "In contrast, the small cell lung cancer cell lines OH1, OH2 and SW2 transcribed all CXCR4 but were CXCR7-negative." (PMID 24770893, 2014). "For instance, the CXCR4-targeting positron emission tomography (PET) agent [68 Ga]PentixaFor has been proven useful for a comprehensive assessment of the current status quo of solid tumors, including adrenocortical carcinoma or small-cell lung cancer." (PMID 35674738, 2022).